SLC4A4 (solute carrier family 4 member 4)
Diseases named in the same sentence as SLC4A4 in open-access papers (continued):
Sharing a sentence is not in itself a finding about the gene and the disease.
cardiovascular disease (1 paper, 2024).
SLC4A4 also shares sentences with these, for which no sentence is quoted: cataract (6 papers); lung carcinoma (5); cardiac hypertrophy (4); gastric cancer (4); metabolic acidosis (3); Blindness (2); diabetes (2); melanoma (2); Nephropathy (2); ovarian carcinoma (2); thyroid cancer (2); Alzheimer disease (1); Arrhythmia (1); autosomal recessive proximal renal tubular acidosis (1); bladder urothelial carcinoma (1); brain edema (1); Cerebral ischemia (1); colorectal adenoma (1); corneal opacities (1); cyst (1); cystic fibrosis (1); deafness (1); dental fluorosis (1); developmental delay (1); enamel hypoplasia (1); exocrine pancreatic insufficiency (1); familial hemiplegic migraine (1); heart failure (1); hepatocellular carcinoma (1); hereditary sensory neuropathy type I (1).
A further 29 diseases each share a sentence with SLC4A4 in 1 paper.